DGKA (diacylglycerol kinase alpha)
Description:
Diacylglycerol kinase that converts diacylglycerol/DAG into phosphatidic acid/phosphatidate/PA and regulates the respective levels of these two bioactive lipids. Thereby, acts as a central switch between the signaling pathways activated by these second messengers with different cellular targets and opposite effects in numerous biological processes. Also plays an important role in the biosynthesis of complex lipids (Probable). Can also phosphorylate 1-alkyl-2-acylglycerol in vitro as efficiently as diacylglycerol provided it contains an arachidonoyl group. Also involved in the production of alkyl-lysophosphatidic acid, another bioactive lipid, through the phosphorylation of 1-alkyl-2-acetyl glycerol.
Synonyms: DGK-alpha; DAGK; DAGK1
Tractability: Small molecule: a high-quality ligand is known. Antibody: its Gene Ontology location is reachable by antibodies, with high confidence. PROTAC: ubiquitination databases record sites on it; its protein half-life has been measured; a small molecule that binds it is known.
Target class: Enzyme; Transferase
Gene: Protein-coding gene on chromosome 12 (55,927,319 to 55,954,027, forward strand). Ensembl gene ENSG00000065357.
Subcellular location: Cytoplasm, cytosol
Subcellular location (Human Protein Atlas): Vesicles; Mitochondria; Nucleoplasm
Pathways (Reactome):
Hemostasis: Effects of PIP2 hydrolysis
Gene Ontology:
Molecular function: ATP-dependent diacylglycerol kinase activity; kinase activity; lipid binding; acylglycerol kinase activity; alkylglycerol kinase activity; calcium ion binding; phospholipid binding
Biological process: diacylglycerol metabolic process; glycerolipid metabolic process; lipid phosphorylation; phosphatidic acid biosynthetic process; intracellular signal transduction; platelet activation; phospholipase C-activating G protein-coupled receptor signaling pathway; signal transduction
Cellular component: cytosol; membrane; plasma membrane
Genetic constraint (gnomAD): Loss-of-function variants: 35 observed, 110.82 expected, observed/expected ratio (o/e) 0.32, 90% interval 0.24 to 0.42. The upper end of that interval is the gene's LOEUF score, 0.42, which puts it in group 1 of 6, group 1 being the genes least tolerant of losing a copy. Missense variants: 665 observed, 967.46 expected, observed/expected ratio (o/e) 0.69, 90% interval 0.64 to 0.73. Synonymous variants: 296 observed, 351.58 expected, observed/expected ratio (o/e) 0.84, 90% interval 0.76 to 0.93.
Homologues: Orthologues: chimpanzee DGKA (99% identical), macaque DGKA (97% identical), pig DGKA (93% identical), rabbit DGKA (93% identical), dog DGKA (93% identical), guinea pig DGKA (92% identical), rat Dgka (83% identical), mouse Dgka (82% identical), tropical clawed frog dgka (65% identical), zebrafish dgkaa (61% identical), zebrafish dgkab (55% identical), Drosophila melanogaster CG34384 (29% identical), and 3 more. Paralogues in human: DGKB (60% identical), DGKG (56% identical), DGKD (31% identical), DGKH (31% identical), DGKK (28% identical), DGKI (27% identical), DGKQ (26% identical), DGKZ (25% identical), DGKE (24% identical).
Diseases named in the same sentence as DGKA in open-access papers:
DGKA is named in the same sentence as 75 diseases in open-access papers, as found by Europe PMC text mining. Sharing a sentence is not in itself a finding about the gene and the disease. The quoted sentences say what the papers report.
melanoma (18 papers, 2014 to 2026). A malignant, usually aggressive tumor composed of atypical, neoplastic melanocytes. "DGKα is probably the isoform most investigated in cancer, being overexpressed in several cancer subtypes, such as acute myeloid leukemia, melanoma, hepatocellular carcinoma, glioblastoma, and so forth." (PMID 40859612, 2026). "Conversely, DGKα promotes proliferation and attenuates apoptosis in hepatocellular carcinoma cells and melanoma, while enhancing epithelial-mesenchymal transition (metastasis) in glioblastoma cells." (PMID 41080753, 2025). "The relationship between DGKα expression and cancer progression has been reported in several cancers, including hepatocellular carcinoma, melanoma, glioblastoma, colon adenocarcinoma, and breast adenocarcinoma." (PMID 40013327, 2025). "DGKα has been reported to generate 16:0/16:0-, 16:0/18:0-, and 16:0/16:1-PA in melanoma cells and 14:1/16:1-, 14:0/16:1-, 14:0/16:0-, 16:1/16:2-, 16:1/16:1-, 16:0/16:1-, 16:0/16:0-, 16:0/18:1-, and 16:0/18:0-PA in T cells." (PMID 41080753, 2025). "In the present study, to explore how DGKα plays reverse roles in cancer cells and T lymphocytes, we searched for the target proteins of 16:0/16:0-PA in human melanoma cells." (PMID 36791913, 2023). "In contrast to T cells, DGKα attenuates apoptosis and promotes the proliferation of melanoma and hepatocellular carcinoma cells and enhances epithelial–mesenchymal transition (metastasis) of glioblastoma." (PMID 36791913, 2023). "The expression of DGKα is increased in several cancer cells with poor prognosis, such as hepatocellular carcinoma, melanoma and glioblastoma." (PMID 37392305, 2023). "DGKα is abundantly expressed in T lymphocytes/thymus and cancer cells, including melanoma, hepatocellular carcinoma and mesenchymal glioblastoma." (PMID 36791913, 2023). "Studies have confirmed that DGKα is highly expressed in several refractory cancer cells, such as melanoma, hepatocellular carcinoma and glioblastoma." (PMID 38033488, 2023). "For example, DGKA is upregulated in melanoma, hepatocarcinoma and glioblastoma, where it contributes to the acquisition of tumor metastatic traits, and induces cisplatin and anti-PD-1 antibody resistance via crosstalk with kinase and transcription networks." (PMID 35115500, 2022). "DGKα activates NF-κB through PKCζ-dependent phosphorylation at Ser-311 of the p65/RelA subunit of NF-κB in AKI melanoma cells." (PMID 34680338, 2021). "In glioblastoma and melanoma cells, DGKα attenuates apoptosis by enhancing the phosphodiesterase (PDE)-4A1–mammalian target of the rapamycin pathway." (PMID 34680338, 2021). "DGKα is abundantly expressed in several cancer cell lines including hepatocellular carcinoma, melanoma, glioblastoma, colon adenocarcinoma, and breast adenocarcinoma cells, enhancing their progression and proliferation, and attenuating apoptosis." (PMID 34680338, 2021). "DGKα is highly expressed in several refractory cancer cells, including melanoma, hepatocellular carcinoma, and glioblastoma cells, attenuates apoptosis, and promotes proliferation." (PMID 34680338, 2021). "(see Section 2.2), DGKα consumes different DG molecular species in AKI melanoma cells (16:0/16:0- and 16:0/18:0-PA) and Jurkat T cells (16:0- and/or 16:1-containing DG species) under starved conditions." (PMID 34680338, 2021). "DGKα is highly expressed in several refractory cancer cells including melanoma, hepatocellular carcinoma, and glioblastoma cells." (PMID 34680338, 2021). "In melanoma cells, DGKα is an antiapoptotic factor that activates nuclear factor-κB (NF-κB) through the atypical protein kinase C (PKC) ζ-mediated phosphorylation of NF-κB." (PMID 34680338, 2021). "On the other hand, using the small molecule inhibitor of DGKs R59022, DGKα was inhibited in glioblastoma, cervical cancer, melanoma, and breast cancer cell lines." (PMID 32722576, 2020).
melanoma (continued). "In contrast, DGKA expression is strongly increased in tumors like melanoma, hepatocarcinoma, and glioblastoma as detected by RNA quantification or immunohistochemistry." (PMID 32477950, 2020). "DGKα, which is abundantly expressed in several cancer cells, such as melanoma, hepatocellular carcinoma, and lymphoma, enhances cell proliferation and inhibits apoptosis." (PMID 32947951, 2020). "siRNA knockdown of DGKA or inhibition of DGKα by small molecule inhibitors for DGKs, R59022 and R59949, has detrimental effects on the proliferation of glioblastoma cells, melanoma, breast cancer, and cervical cancer cells." (PMID 30128205, 2018). "In melanoma cells, DGKα positively regulates tumor necrosis factor-α-dependent nuclear factor-κB (p65) activation via the PKC ζ-mediated Ser311 phosphorylation of p65." (PMID 27583247, 2016). "Several reports indicate that DGKα sustains survival of cancer cells, including lymphoma, melanoma and hepatoma." (PMID 25339152, 2014). "PA species generated by DGKα in melanoma and T cells overlap each other." (PMID 36791913, 2023). "DGKα prevents apoptosis through the PKCζ–NF-κB pathway in melanoma cells." (PMID 36791913, 2023). "In addition to DGKδ, PA species produced by DGKα in melanoma and T cells are also different from each other." (PMID 32947951, 2020). "Similarly, compound A, which specifically inhibits type I DGKs and especially DGKα, induced apoptosis and reduced viability of melanoma and several other cancer cell lines." (PMID 32722576, 2020). "DGKα is highly expressed in hepatocellular carcinoma and melanoma cells." (PMID 27583247, 2016). "Several studies pointed out DGKα involvement in cancer showing that its activity is necessary in vivo for glioblastoma and hepatocellular carcinoma progression, and in vitro for proliferation and survival of endometrial carcinoma, anaplastic large cell lymphoma, and melanoma." (PMID 24887021, 2014). "Previous studies have shown that DGKα preferentially produces SFA- and/or MUFA-containing PAs including 16:0/16:0-PA in AKI melanoma cells." (PMID 41080753, 2025). "DGKα generates SFA- and/or MUFA-containing PAs, such as 16:0/16:0-, 16:0/18:0-, and 16:0/16:1-PA, in serum-starved AKI melanoma cells." (PMID 36791913, 2023). "DGKα commonly generates SFA- and/or MUFA-containing PA species, for example, 16:0/16:0-PA in melanoma and T cells." (PMID 36791913, 2023). "We previously reported that DGKα preferentially generated SFA/MUFA-PA species, such as 16:0/16:0-, 16:0/18:0-, and 16:0/16:1-PA, in AKI human melanoma cells." (PMID 36791913, 2023). "Recently, LC-MS revealed that the production of palmitic acid (16:0)-containing PA species such as 16:0/16:0- and 16:0/18:0-PA were attenuated by CU-3, a DGKα-selective inhibitor, in AKI melanoma cells under starved conditions." (PMID 32947951, 2020). "We recently found that DGKα preferentially generated saturated fatty acid (SFA)- and/or monounsaturated fatty acid (MUFA)-containing PAs, such as 16:0/16:0-, 16:0/18:0-, and 16:0/16:1-PA in serum-starved AKI melanoma cells." (PMID 36791913, 2023). "DGKα is highly expressed in cancer cells, such as melanoma and hepatocellular carcinoma cells, but not in normal melanocytes or hepatocytes." (PMID 36791913, 2023). "Intriguingly, knockdown of DGKα in non-cancerous cells, such as astrocytes and fibroblasts, showed no form of cytotoxicity as revealed in both glioblastoma and melanoma cells." (PMID 32722576, 2020). "Expression of DGKα has been reported to be upregulated in melanoma cells (but not in noncancerous melanocytes), lymphoma, hepatocellular carcinoma, breast cancer cells, and glioblastoma cells where DGKα promotes cancer cell survival, proliferation, migration, and invasion." (PMID 30128205, 2018). "Taken together, these results strongly suggest that SFA- and/or MUFA-containing PAs produced by DGKα selectively target HSP27 and regulate its cancer-progressive function in melanoma cells but not in T cells." (PMID 36791913, 2023).
melanoma (continued). "In summary, in the present study, we demonstrated that SFA/MUFA-PAs, which are produced by DGKα in cancer cells, strongly bind to HSP27, which is highly expressed in melanoma cells but not in T cells and attenuates its oligomer formation." (PMID 36791913, 2023). "For DGKA, this process might be cell type specific as the spectrum of DAG species converted in AKI melanoma cells is not identical to the one observed in normal human dermal fibroblasts." (PMID 32477950, 2020).
glioblastoma (17 papers, 2014 to 2026). The most malignant astrocytic tumor (WHO grade IV). "In glioblastoma, DGKα has been associated with tumor proliferation via regulation of mTOR expression and activity." (PMID 36358678, 2022). "In glioblastoma cells, DGKα production of PA has been associated with inhibition of apoptosis and regulation of hypoxia-inducible factor 1-α (HIF1-α) and mammalian target of rapamycin (mTOR) oncogenic pathways." (PMID 36358678, 2022). "PA produced by DGKα activates the geranylgeranyltransferase (GGTase) I–RhoA and consequently GGTase I–RhoA–NF-κB pathways in glioblastoma cells." (PMID 34680338, 2021). "Several authors describe that the growth of glioblastoma and other cancers can be impeded with DGKA inhibitors in cell cultures and in xenografts." (PMID 32477950, 2020). "Understanding PMT regulation more broadly may aid in identifying treatments that preferentially target specific subtypes, as demonstrated for CDK4/6 or EZH2 inhibition for proneural glioblastomas and DGKα or BMI-1 inhibition for mesenchymal glioblastomas." (PMID 38337036, 2024). "Based on prior reports, DGKα inhibition may be particularly relevant for the treatment of glioblastoma (GBM), the most common brain malignancy and one which is incurable with current therapies." (PMID 35267577, 2022). "Therefore, DGKα confers the mesenchymal phenotype, which is characterized by aggressiveness and treatment resistance, to glioblastoma cells." (PMID 34680338, 2021). "Indeed, in glioblastoma in vivo tumor models, the same authors showed that DGKα inhibition decreases angiogenesis, tumor growth, and survival of mice with tumors." (PMID 32722576, 2020). "Indeed, DGKα inhibition by Ritanserin induced cell death in glioblastoma stem cells and this was partially mediated by apoptosis." (PMID 32722576, 2020). "DGKα knockdown decreased both total and phosphorylated forms of mTOR, hypoxia-inducible factor 1-alpha (HIF1α), c-Myc levels, and phosphorylation of Akt in glioblastoma cells." (PMID 32722576, 2020). "Studies have shown that ritanserin inhibits C-RAF to cause apoptosis in lung cancer cells and prevents glioblastoma multiforme (GBM) and pancreatic cancer spread by modifying DGKα, which promotes the mesenchymal phenotype." (PMID 37392305, 2023). "For instance, inhibition of DGKα expression via molecular genetics techniques such as the use of small-interfering RNA against DGKα or the use microRNA-297 showed promise as evidenced by the suppression of the proliferation of colon and breast cancer as well as glioblastoma." (PMID 36358678, 2022). "Increasing evidence points to DGKα as a critical node in oncogenic signaling and as a putative novel therapeutic target in cancer: inhibition or silencing of DGKα has been shown to reduce tumor growth and mortality in glioblastoma and hepatic carcinoma xenograft models." (PMID 24887021, 2014). "Diacylglycerol kinase α (DGKα) inhibition may be particularly relevant for the treatment of glioblastoma (GBM), a relatively common brain malignancy incurable with current therapies." (PMID 35267577, 2022). "Biochemical inhibition or silencing of DGKA was reported to reduce HIF-1α and mTOR signaling by limiting PA in glioblastoma cells." (PMID 32477950, 2020). "Similarly, miR-297 and hypoxia-activated hnRNP L were shown to regulate translation of diacylglycerol kinase-alpha (DGK-α) mRNA in human glioma cells via the same mechanism reported for the VEGFA mRNA switch, thereby promoting glioblastoma progression." (PMID 31741723, 2019). "Additionally, a study testing the importance of DGKα in glioblastoma multiforme (GBM) cells found that concurrent administration of the relatively non-specific DGKα inhibitor R59022 resulted in decreased growth of intracranially injected GBM tumors." (PMID 27800476, 2016).
hepatocellular carcinoma (17 papers, 2014 to 2025). A malignant tumor that arises from hepatocytes. "DGKα is increased in 20% of hepatomas, where it is associated with high Ki67 levels and recurrence rate." (PMID 25339152, 2014). "Furthermore, immunohistochemical analyses in tissue samples from patients with hepatocellular carcinoma revealed an association of high DGKA expression and high expression of the cellular proliferation marker Ki-67." (PMID 32477950, 2020). "For instance, mutations in the DGKα gene can drive pancreatic cancer as well as promote hepatocellular carcinoma (HCC) progression by activating the mitogen-activated protein kinase (MAPK) pathway." (PMID 32722576, 2020). "Reportedly, DGKα is intimately involved in liver function under pathophysiological conditions and positively regulates proliferation and invasion of human hepatocellular carcinoma cells." (PMID 38105414, 2024). "High expression of diacylglycerol kinase alpha (DGKα) is a prognostic factor for the recurrence of hepatocellular carcinoma." (PMID 38716625, 2024). "We analyzed the 5′-upstream region (3.4 kb) of the DGKα gene and revealed that the transcription of DGKα is differently regulated in human Jurkat T cells and human hepatocellular carcinoma HepG2 cells." (PMID 34680338, 2021). "In contrast to the T cells in which DGKα inhibition activates the Ras pathway, the inhibition of DGKα suppresses Ras in the hepatocellular carcinoma cells." (PMID 32962151, 2020). "DGKα expression is involved in hepatocellular carcinoma progression and is a positive regulator of the proliferative activity of hepatocellular carcinoma through the Ras/Raf/MEK/ERK pathway." (PMID 27583247, 2016). "It is tempting to suggest a function for DGKα promoting Src signaling in this cancer type, since there is mounting evidence of a role for Src in hepatocellular carcinoma development." (PMID 25339152, 2014). "Moreover, DGKα promotes hepatocellular carcinoma proliferation via activation of the Ras–Raf–MAPK/ERK kinase–ERK pathway." (PMID 36791913, 2023). "DGKA could enhance hepatocellular carcinoma progression via Ras-Raf-MEK-ERK pathway and promote platinum resistance by activating c-JUN-WEE1 signaling in ovarian cancer." (PMID 35957912, 2022). "DGKA is highly expressed in various human hepatocellular carcinoma cell lines." (PMID 32477950, 2020). "Expression of OGT, C8orf33, DGKA and SMTN has been correlated with cardiovascular disease, hepatocellular carcinoma, acute myeloid leukemia and hypertension, respectively." (PMID 37026480, 2023). "DGKα acts as an enhancer of proliferative activity through the Raf–MEK–ERK pathway and consequently exacerbates hepatocellular carcinoma progression." (PMID 34680338, 2021).